IL10 (interleukin 10)
Diseases named in the same sentence as IL10 in open-access papers (continued):
Sharing a sentence is not in itself a finding about the gene and the disease.
colitis (continued). "In established colitis, this preconditioning enables the same antigen to polarize immune responses toward regulatory pathways (e.g., IL-10 production) that counteract TNBS-driven Th1/Th17 inflammation, consistent with the hygiene hypothesis." (PMID 40830617, 2025). "Furthermore, the supplementation of HLH and HLL significantly boosted (p < 0.05) the production of the anti-inflammatory cytokine IL-10, enhancing the inflammatory response management in the colitis models." (PMID 40001993, 2025). "Furthermore, goblet cell loss is a common feature of Crodentium-triggered colonic inflammation, as well as genetically-driven colitis observed in IL-10-/- mice." (PMID 41047099, 2025). "It has been suggested that LGG alleviation of colitis likely relies on elevated IL-10 in the intestine but with unknown cellular source and the underlying mechanisms." (PMID 39895628, 2025). "This study demonstrated that the expressions of PANoptosis-related marker proteins were significantly elevated in patients with CD, IL-10 KO colitis mice, and LPS + ATP-induced in vitro inflammation models, which strongly suggested the presence of PANoptosis under inflammatory conditions." (PMID 40520022, 2025). "In fact, the lack of IL-10 production by Treg cells induces inflammation in the colon and il10-deficient mice spontaneously develop colitis." (PMID 41155360, 2025). "TRF delayed colitis onset reduced the expression of inflammatory markers and increased the expression of clock genes in the intestine, and increased gut microbiota rhythmicity in IL-10-/- mice." (PMID 39843997, 2025). "Moreover, levels of pro-inflammatory cytokines including IL-6, IL-1β, and TNF-α were notably reduced, whereas anti-inflammatory cytokine IL-10 was notably increased after YTA treatment in colitis mice." (PMID 41476793, 2025). "Furthermore, Lactobacillus has been shown to elevate IL-10 levels by modulating the development and maturation of regulatory T cells in colitis." (PMID 39936162, 2025). "The marked changes in TNF and IL-10-specific signaling due to DSS-colitis provide evidence that inflammation in the body may lead to a reduction in the signal-to-noise at the individual neuron level." (PMID 40268933, 2025). "First, the colitis model was induced, and IL-10 engineered MSCs were injected intravenously." (PMID 39990215, 2025). "It has been reported that Houttuynia Chordata, a traditional medicinal plant, decreased inflammatory cytokines, such as IL-6 and TNF-α, and increased the level of anti-inflammatory IL-10 and various tight junction proteins in a dextran sulfate sodium-induced colitis model." (PMID 40149930, 2025). "Probiotic Clostridium butyricum promotes IL‐10 production by CD11b+CD11c(int) intermediate F4/80+ intestinal macrophages via the TLR2/MyD88 signaling pathway in dextran sodium sulfate (DSS)‐induced colitis." (PMID 38604998, 2024). "Secondly, B. bifidum has immune-regulatory functions, inhibiting the expression of inflammatory factors interleukin (IL)-1β, tumor necrosis factor (TNF)-α, IL-6, and interferon (IFN)-γ, while promoting IL-10 expression, thus facilitating gut damage repair in colitis mice." (PMID 39525506, 2024). "Therefore, CrF‐EV injection regulated colitis and mesenteritis of Il‐10−/− mice through miR‐132‐3p/RASA1/ERK1/2‐dependent improvement of lymphatic endothelial functions." (PMID 39623906, 2024). "To this end, we next aimed to determine spontaneous colitis development in Il10−/− mice bred in the presence of a colitogenic SPF microbiota, that showed a distinct beta diversity compared with MB1, including an enrichment of Helicobacter on genus level (referred to as MB2)." (PMID 38839272, 2024). "Herein, we further investigated whether CrF‐EVs affect colitis and mesenteritis in Il‐10−/− mice through the regulation of lymphatic functions." (PMID 39623906, 2024).
colitis (continued). "Furthermore, the immunomodulatory properties of genistein are supported by an increase in broilers’ serum IgG and IgM concentrations and the restoration of IL-10 in the colon of mice with colitis." (PMID 38928362, 2024). "In a TNBS-induced colitis model, treatment with Lactobacillus peptidoglycan increased the number of Tregs in mesenteric lymph nodes and elevated IL-10 expression in the colonic mucosa, implying that NOD2 activity within the intestinal mucosa fosters a milieu conducive to immune tolerance." (PMID 38507159, 2024). "Furthermore, in the IL10−/− mouse model of chronic intestinal inflammation, the deletion of MyD88 protected IL10−/− mice from spontaneous commensal-dependent colitis." (PMID 38946731, 2024). "This was confirmed by different mouse models, such as IL-10 deficient mice without colitis symptoms under germ-free conditions." (PMID 38397751, 2024). "Nevertheless, IL-10 signaling in macrophages—an innate immune cell type that is important in attacking invading pathogens and mounting the host response to infections—has been shown to protect against colitis development." (PMID 39132450, 2024). "A previous study indicated that Lactobacillus johnsonii could relieve experimental colitis by activating native macrophages and releasing IL-10." (PMID 38399785, 2024). "In an IL10-deficient mouse spontaneous colitis model, NE-52-QQ57 did not exhibit significant efficacy but demonstrated a trend towards improvement for several disease parameters such as histopathology, inflammation, and hyperplasia scores." (PMID 39336742, 2024). "Therefore the colitis development we observed in Il10−/− mice under specific pathogen-free (SPF) conditions of the local mouse facility (referred to as MB1) was generally mild." (PMID 38839272, 2024). "In agreement with a previous report, our data indicated that IPA significantly enhances epithelial barrier integrity and decreases inflammation in two different murine models of intestinal inflammation including DSS-induced colitis and IL-10−/− spontaneous colitis." (PMID 38504383, 2024). "Notably, during C. rodentium infection, the inhibition of IL-10 production results in severe colitis driven by macrophage-derived IL-23." (PMID 39379604, 2024). "In a mouse model of DSS-induced colitis, it was shown that S. cerevisiae supplementation increased the expression of anti-inflammatory cytokines (IL-4 and IL-10), while reducing the disease activity index and the expression of pro-inflammatory cytokines (TNF-α, IL-6 and IL-17F)." (PMID 38540191, 2024). "It is noteworthy that neither the IL10‐deficient nor TCRα‐deficient mice develop colitis under germ‐free conditions, which implicates the microbiota in colitis development." (PMID 38992956, 2024). "In addition, chylomicrons‐simulating sustained drug release in mesenteric lymphatics effectively mitigated Crohn‐like colitis in Il10−/− mice." (PMID 39623906, 2024). "Notably, ILA, IPA, and IAA possess the ability to mitigate intestinal inflammation and modulate the gut microbiota in both DSS-induced and IL-10−/− spontaneous colitis models." (PMID 38504383, 2024). "Perilla seed oil, rich in α-linolenic acid, reduces colitis by suppressing inflammatory markers including interleukin-1 (IL-1), interleukin-2 (IL-2), interleukin-4 (IL-4), interleukin-5 (IL-5), interleukin-6 (IL-6), and interleukin-10 (IL-10)." (PMID 39022021, 2024). "Butein, a major constituent of Toxicodendron vernicifluum ameliorated colitis in IL-10(-/-) mice by reducing the colonic inflammatory score by > 50%, reducing the expression levels of IL-6, IL-1β, IFN-γ pSTAT3 and MMP-9, also inhibiting IL-6-induced activation of STAT3 in Colo 205 cells." (PMID 39494333, 2024). "Compared with the model group, different concentrations of oat and bran treatment groups could promote the expression of IL-10 and inhibit the gene expression of IL-6 and TNF-α, thus mitigating the mucosal damage caused by DSS-induced colitis." (PMID 39770986, 2024).
colitis (continued). "IL-10 gene knockout is one of the earliest ways employed to establish colitis models for animals, indicating that IL-10 serves as a critical inflammatory marker in the context of colitis." (PMID 39458282, 2024). "In addition, acetylcholine and MDSCs were able to establish a neuroimmune regulatory pathway via increasing IL-10 release from M-MDSCs to alleviate colitis inflammation." (PMID 37733169, 2024). "Interestingly, we also observed that the anti-inflammatory cytokine IL-10 levels were elevated in response to DSS-induced colitis and subsequently diminished following administration of SBP." (PMID 38732527, 2024). "High titer neutralizing anti-IL-10 antibodies were identified in a child with infantile-onset severe colitis that phenotypically resembled an inborn error of the IL-10 pathway, despite the absence of pathogenic mutations." (PMID 39083772, 2024). "Our data showed that treatment with PD-L1-Fc/Oxi-αCD nanoparticles increased the content of SCFAs in the feces of mice with colitis, which was accompanied by an increase in the proportion of some T lymphocytes in the colonic lamina propria, as well as an increase in IL-10 concentrations." (PMID 38396052, 2024). "Furthermore, the gut microbiome modulated by T. spiralis exhibited enhanced goblet cell differentiation and elevated IL-10 levels, ultimately ameliorating experimental colitis." (PMID 39495798, 2024). "However, in the same model of spontaneous colitis (IL-10 knockout mice), L. plantarum treatment decreases the expression and transport activity of PepT1 in the colon." (PMID 39203856, 2024). "Contrary to the groups of C57BL/6 mice subjected to the induction of experimental colitis where local IL-10 levels were similar to NC, local IL-10 levels remained elevated in recovered BALB/c mice (compared to NC: p ˂ 0.005 for rBL0.1, p ˂ 0.001 for rBL1, rBL10, and PC)." (PMID 38892639, 2024). "Extracellular vesicles (EVs) derived from adipose tissue‐derived stem cells in creeping fat (CrF) improve lymphatic functions and increase mesenteric lymphatic vessel density of Il‐10‐/– mice, leading to decreased colitis and mesenteritis through the miR‐132‐3p/RASA1 /ERK1/2 axis." (PMID 39623906, 2024). "Additionally, hydroxytyrosol has been shown to lower levels of IL-1β, IL-6, and TNF-α and increase the level of the anti-inflammatory cytokine IL-10 to ameliorate intestinal inflammation in mice colitis models." (PMID 38891778, 2024). "Interestingly, Lactobacillus isolated from Chinese cabbage increased IL10 anti-inflammatory activity against colitis in DSS mice." (PMID 38779039, 2024). "Also, sinapic acid reduces serum levels of proinflammatory cytokines (TNF-α, IL-1β, IL-6, IL-17α, IL-18, and interferon (IFN)-γ) and increases anti-inflammatory cytokines (IL-4 and IL-10) in Kunming mice with DSS-induced colitis." (PMID 38732594, 2024). "However, colitis severity in Il10−/−Mdr2−/− mice with concomitant sclerosing cholangitis was significantly reduced compared with Il10−/− mice." (PMID 38839272, 2024). "Concerning genes with anti-inflammatory effects, significantly increased levels of IL-10 (3.8 ± 2.0 vs. 0.9 ± 0.3, p < 0.05) and PPARγ (0.8 ± 0.0 vs. 0.6 ± 0.0, p < 0.05) mRNA were observed in the colon of rats with colitis treated with the synbiotic compared to untreated animals." (PMID 39409061, 2024). "Similarly, EEN had clear benefits in IL-10 knockout mice infected with Helicobacter trogontum as a bacterial trigger to induce colitis." (PMID 39339655, 2024). "Importantly, for the first time, we demonstrated the beneficial effects of nighttime-restricted feeding (RF) on circadian colon functions, the microbiome, IBD progression and survival of IL-10−/− mice, a well-described mouse model of colitis." (PMID 38918576, 2024). "Genistein-induced colitis mice exhibited heightened expression of Arg-1 and IL-10 in M2 macrophages compared to those treated with PBS, although the precise mechanism underlying this shift remains unclear." (PMID 39668979, 2024).
colitis (continued). "However, another newly isolated strain of Akk in 2017 has been shown to exacerbate colitis in IL-10-/- mice." (PMID 39741950, 2024). "We found that Il10−/− and Il10−/−Mdr2−/− mice developed an overall mild colitis." (PMID 38839272, 2024). "The combination therapy of Bacteroides thetaiotaomicron and Faecalibacterium prausnitzii is superior to mono-bacterial therapy in ameliorating colitis in mice, of which mechanism may involve promoting lecithin and inducing IL-10 production of intestinal Tregs." (PMID 38502145, 2024). "In the murine model of oxazolone-induced colitis, CD1d expressed on bone marrow-derived cells elicits pathogenic effects by mediating activation of NKT cells, while CD1d expression by IECs leads to protection mediated by IL-10 production." (PMID 38579449, 2024). "Consistent with our hypothesis, RF further ameliorated the IBD-like colitis phenotype in IL-10−/− mice and substantially enhanced their survival rate." (PMID 38918576, 2024). "Interestingly, Il10−/−Mdr2−/− mice with a concomitant experimental sclerosing cholangitis developed significantly reduced colitis compared with Il10−/− mice." (PMID 38839272, 2024). "Moreover, genetically engineered L. lactis strains harboring and delivering anti-TNF nanobody, ovalbumin, DQ8 gliadin epitope, and GAD65 and IL-10 were used as vaccine against colitis, autoimmune diseases, celiac disease, and type 1 diabetes, respectively." (PMID 38495751, 2024). "In models of spontaneous colitis in IL-10-knockout (KO) mice (IL-10 is a major immunosuppressive cytokine), STING deficiency again was associated with reduced intestinal inflammation, decreased production of pro-inflammatory cytokines, and a reduction in spontaneous polyp formation." (PMID 39050748, 2024). "This may provide insight into the co-administration of IL-10 with anti-TNF-α agents in the treatment of inflammatory infectious diseases like colitis and IBD toward enhanced therapeutic outcomes, with reduced inflammation and improved tissue healing." (PMID 38251210, 2024). "IL-10 is a key immunosuppressive cytokine that regulates intestinal homeostasis, and its restriction of a pro-inflammatory response plays an important role in reducing the severity of colitis." (PMID 38892496, 2024). "In IL-10 knockout mice, this has been shown to result in colitis." (PMID 39249550, 2024). "Similarly, in an IL-10−/− colitis model, mice fed a 7% (w/w) fish oil diet exhibited increased colitis scores, aberrant crypt counts, colon dysplasia, and elevated COX-2 expression in colon tissue." (PMID 39652552, 2024). "As MMTV requires a viral superantigen to replicate in the gut-associated lymphoid tissue prior to the development of systemic infection, we evaluated whether MMTV may contribute to the development of colitis in the IL-10−/− model." (PMID 36869359, 2023). "The central hypothesis this study sought to test was whether sex plays a role in the phenotype of colitis developed in the murine model of IL-10−/− mice." (PMID 37373511, 2023). "The aim of this study was to address the hypothesis that MMTV infection contributes to development of spontaneous colitis observed in the IL-10−/− model." (PMID 36869359, 2023). "D3 may also be an important regulator of IBD, as D3 deficiency in murine regulatory T-cells diminished inflammatory manifestations of colitis by attenuating IL-10 production and reducing the acquisition of gut-tropism in these cells." (PMID 36757901, 2023). "Since a deficiency in IL-10 levels exacerbates DSS-induced colitis, IL-10 supplementation may become an alternative treatment to improve colitis." (PMID 38201294, 2023). "This altered sensitivity to disease observed in TgVil1-Itln1 may be a consequence of mucus layer thinning, similar to the spontaneous colitis reported in Muc2−/− mice and in gnotobiotic Il10−/− mice colonized with A. muciniphila." (PMID 36413219, 2023).
colitis (continued). "Additionally, In vivo experiments verified that knocking down circPRKAR1B and methyltransferase‐like 3 (METTL3) ameliorated experimental colitis in mice with IL‐10‐knockout (IL‐10‐KO)." (PMID 37679886, 2023). "The beneficial effect of PARP1 inhibition was also confirmed in various animal models including dinitrobenzene sulfonic acid (DNBS) and trinitrobenzene sulfonic acid (TNBS) induced acute and chronic colitis and spontaneous chronic colitis developed in IL-10 knockout mice." (PMID 37457706, 2023). "Mice with Treg cells lacking IL-10 or IL-10Rα are prone to spontaneous colitis, highlighting the role of IL-10 in enabling Treg cells to suppress pathogenic Th17 cell responses in colitis." (PMID 38137450, 2023). "Moreover, colitis symptoms are ameliorated by manipulation of the microbiota to increase IL-10 producing macrophage numbers." (PMID 36675038, 2023). "Notably, mice that lack the anti-inflammatory cytokines IL-2 or IL-10 exhibit the development of spontaneous colitis, underscoring the crucial role of these cytokines in preventing inflammatory responses in the gut." (PMID 38137450, 2023). "Subsequently, we further analyzed the level of inflammatory factors in colon tissue and found that the pro-inflammatory cytokines IL-1β, IL-6, IL-12, IL-17 and TNF-α were increased and the anti-inflammatory cytokine IL-10 was decreased in the colon of DSS-induced colitis." (PMID 37438752, 2023). "Moreover, the deletion of macrophage-specific IL-10R1 worsens the disease severity in the DSS-induced colitis animal model, the observation of which is consistent with the IL-10 or IL-10R1 knot-out mice." (PMID 36767519, 2023). "Notably, the colitis-induced group treated with HM sEVs or ω3 OXLP had elevated levels of anti-inflammatory cytokines such as IL-10 and IL-1 receptor antagonist (IL-1Ra)." (PMID 38054009, 2023). "In liver, colitis caused both oxidative (MDA, SOD, and GSH) and inflammatory damage (IL-10)." (PMID 37577725, 2023). "However, antibiotics exacerbated colitis in interleukin 10-knockout mice at 8 weeks of age, and germ-free mice are susceptible to colitis." (PMID 37040489, 2023). "However, expression of colon cytokines including IL-10 suggested that resolution of WD-induced colon inflammation after return to a healthier diet led to an enhanced anti-inflammatory milieu." (PMID 37305694, 2023). "Indigo could increase IL-10 and IL-22 expression in isolated LP monocytes from colitis rats induced by TNBS and DSS." (PMID 37675045, 2023). "Regulated the colitis i gut microbiota, protected the mucosal barrier system, improved the antioxidant levels, decreased the weight loss and DAI, reduced the expression of TNF-α, up-regulated the expressions of IL-10." (PMID 37485519, 2023). "Indeed, loss of mTOR signaling in DCs blocks IL-10 generation by cDC2s and increases sensitivity to DSS-induced colitis." (PMID 36675038, 2023). "According to the results, VK2 restored the colon lengths, improved the colonic histopathology, reduced the levels of proinflammatory cytokines (such as IL-1β, TNF-α, and IL-6), and boosted the level of the immunosuppressive cytokine IL-10 in the colon tissues of the colitis mice." (PMID 36769323, 2023). "The results revealed that L. plantarum, COS, and the synbiotics alleviated the symptoms of mice colitis and inhibited the changes in short-chain fatty acids (SCFAs), tumor necrosis factor-α (TNF-α), interleukin (IL)-1β, IL-6, IL-10, and myeloperoxidase (MPO) caused by DSS." (PMID 37297494, 2023). "1,25(OH)2D3 treatment suppresses colitis in IL-10 knockout mice and DSS-treated mice." (PMID 36834927, 2023). "IL-10, secreted by T helper cells, macrophages, dendritic cells and neutrophils is highly relevant to IBD, as also demonstrated in IL-10 −/− deficient mice that spontaneously develop very early colitis." (PMID 37049615, 2023).